MTOR (mechanistic target of rapamycin kinase)
Diseases named in the same sentence as MTOR in open-access papers (continued):
Sharing a sentence is not in itself a finding about the gene and the disease.
glioma (continued). "Further supporting that mTOR inhibition may represent a relevant therapy for brain tumors in NF1, preliminary clinical studies confirmed unequivocal efficacy of rapamycin and its analogs to reduce the growth of plexiform neurofibroma or low-grade glioma observed in some patients with NF1." (PMID 34576341, 2021). "Moreover, a recent study showed that autophagy induction by the mammalian targets of rapamycin (mTOR) inhibitor rapamycin triggers GSC differentiation and enhances their radiosensitization in vitro and in vivo, with rapamycin thus becoming a promising tool for radiosensitization in glioma." (PMID 33762015, 2021). "A current report also JMJD2A depletion reduced protein synthesis and enhanced the protein synthesis suppression observed with mTOR inhibitors, which paralleled an increased sensitivity to drugs, indicating that JMJD2A may serve as an adjuvant target for protein synthesis inhibition in glioma." (PMID 32256210, 2020). "In our previous study, we also found that miR-128 could target to IGF-1-mediated mammalian target of rapamycin (mTOR) signaling in temozolomide-induced glioma cell apoptotic death, suggesting that microRNAs play critical roles in regulating IGF-1 signaling involved in glioma progression." (PMID 28389653, 2017). "If mTOR pathways are normally down-regulated in tumor hypoxia, drug inhibitors of the mTOR pathway may not be a successful treatments for high-grade gliomas as the target may already be depressed, a conclusion supported by current clinical trials of mTOR inhibitors in glioblastoma patients." (PMID 22276931, 2012). "In gliomas, the PI3K/AKT/mTOR pathway helps to induce invasion and angiogenesis in cells, and patients with activated PI3K/AKT/mTOR pathway have a worse prognosis than those without carcinogenic activation of the pathway." (PMID 33676540, 2021). "CDK4/6 inhibitor Palbociclib combined with mTOR inhibitor MLN0128 suppresses the proliferation of ER negative breast cancer cells and Glioma." (PMID 31358010, 2019). "Our results suggest that SLCP induced autophagy markers greater than natural Cur, as well as the inhibition of mitophagy and the significant disruption of the PI3K-Akt/mTOR pathway in all three GBM cells, without significant effects on C6-glioma and N2a cells." (PMID 30669284, 2019). "The capacity of sirolimus to inhibit mTOR and induce autophagy was confirmed in U87MG, T98G, and U373 MG glioma cells, where inhibition of the PI3K/AKT/mTOR pathway led to the induction of autophagy without activating apoptosis." (PMID 30486451, 2018). "In contrast, mTOR inhibitors -TEM and TOR were non-toxic at concentrations that were effective in reducing invasiveness suggesting their targeted action in glioma cells." (PMID 26940200, 2016). "Perhaps even more disappointingly, clinical studies evaluating combinations of mTOR and EGFR inhibitors in patients with recurrent glioma demonstrated limited responses and these were not sustained." (PMID 23555046, 2013). "Despite the prevalence and apparent reliance on PI3K signaling in glioma, PI3K inhibitors exert cytostatic rather than cytotoxic effects in glioma cell lines and xenografts even when combined with inhibitors of the epidermal growth factor receptor (EGFR) and mTOR." (PMID 35163279, 2022). "However, the expression of mTOR, p-mTOR, ATG5, ATG12 and Beclin-1 in glioma cells was not increased after Co3O4 NPs treatment, which confirmed that Co3O4 NPs did not induce autophagy." (PMID 34683892, 2021). "In contrast to a previous study, in which the PI3K/AKT/mTOR signalling pathway was shown to be involved in anti-cancer agent-induced autophagy in glioma, we found that ABA-induced autophagy in glioblastoma cells is independent of the PI3K/AKT/mTOR signalling pathway." (PMID 32577848, 2021).
glioma (continued). "MiR-128 overexpression can promote glioma cell apoptosis in GBM cells by activating caspase-3-9, degrading poly-(ADP ribose) polymerase, producing ROS, lowering mitochondrial membrane potential, and inducing nonprotective autophagy through mTOR inhibition." (PMID 34204169, 2021). "Furthermore, the mRNA and the protein level of HuR were markedly reduced in both GSCs and non-GSCs glioma cells after AKT and mTOR-siRNA transfection." (PMID 27166258, 2016). "The efficacy of PI3K/Akt/mTOR pathway inhibitors in combination with TRAIL has been previously demonstrated, while the effect of BKM120 and TRAIL co-treatment has not been examined in glioma." (PMID 26044191, 2015). "However, when mTOR was inhibited with rapamycin, JMJD2A overexpression could not affect the proliferation and colony formation of glioma cells." (PMID 32256210, 2020).
hepatocellular carcinoma (798 papers, 2007 to 2026). A malignant tumor that arises from hepatocytes. "Some studies indicated that 67 dysregulated lncRNAs associated with the PI3K/AKT/mTOR pathway show oncogenic or anti-oncogenic effects in hepatocellular carcinoma by regulating epigenetic, transcriptional, and post-transcriptional levels." (PMID 40387965, 2025). "CircZKSCAN1 encodes circZKSaa, which sensitizes hepatocellular carcinoma cells to sorafenib via ubiquitination of mTOR." (PMID 40387965, 2025). "Meanwhile, the absence of intra-tumoral TLS was associated with a worse prognosis and mTOR signaling activation in hepatocellular carcinoma with LT." (PMID 41459486, 2025). "By targeting the mTOR pathway, it increases the susceptibility of hepatocellular carcinoma cells to chemotherapeutic agents effectively in an orthotopic HCC mouse model." (PMID 38673047, 2024). "The interaction between FBXW7 and mTOR, facilitated by circZKSCAN1-encoded circZKSaa, was verified to boost mTOR ubiquitination in hepatocellular carcinoma (HCC), consequently suppressing the PI3K/AKT/mTOR pathway." (PMID 38397395, 2024). "The combination of alpelisib, a selective PIK3CA inhibitor, with mTOR inhibitors has also shown a synergistic efficacy in PIK3CA-mutated (H1047R) hepatocellular carcinoma." (PMID 38344201, 2024). "In rat hepatoma cells, the mTOR pathway has been established as intricately linked to the phosphorylation of serine residues within IRS-2, particularly Ser907 and Ser675." (PMID 38248343, 2024). "A cross-talk exists between KRAS mutation and MTOR hyperactivated mouse model in hepatocellular carcinoma (HCC), which acts through a paternally expressed-3 (PEG3)-mediated-signaling pathway." (PMID 39056802, 2024). "S100A10 regulates apoptosis and viability of hepatocellular carcinoma cells probably associated with ANXA2/Akt/mTOR pathway." (PMID 37420211, 2023). "The PI3K/AKT/mTOR pathway, which has been previously implicated in hepatocellular carcinoma carcinogenesis." (PMID 36817123, 2023). "Both dysregulation of mechanistic target of rapamycin (mTOR) signalling and DNA methylation patterns have been shown to be closely associated with tumor progression and serve as promising targets for hepatocellular carcinoma (HCC) therapy." (PMID 37088830, 2023). "Hippo signaling pathway effector Yes-associated protein 1 (YAP), activated by PGE2, promotes hepatocellular carcinoma progression by upregulating the AKT/mTOR/SREBP1 signaling pathway." (PMID 36969840, 2023). "Background & Aims: Abnormal activation of mTOR through loss of tuberous sclerosis complex (Tsc) frequently occurs in hepatocellular carcinoma (HCC)." (PMID 36451866, 2022). "mTOR is an important pathway in Hepatocellular carcinoma that is linked to less-differentiated tumors, bad prognosis, and earlier recurrence independently of the underlying etiology of liver cancer." (PMID 36558112, 2022). "Ye et.al reported the involvement of mTOR inhibition in the BT-induced inhibition of cell proliferation and growth in hepatocellular carcinoma cells, but the underlying mechanism was unclear." (PMID 34221237, 2021). "In fact, over-expression of integrin β4 has been positively associated with Akt-mTOR signaling and lung metastases of hepatocellular carcinoma." (PMID 31167517, 2019). "This study has provided some compelling evidence that liver tumor formation in mouse models of metabolic syndrome and NASH, and in patients with hepatocellular carcinoma with NASH background is closely linked to the activation of mTOR pathways." (PMID 31614491, 2019). "Since we only quantified one modification site on mTOR, we mutated this lysine, K2066, to arginine and assessed the effect of this mutation on autophagy induction in a human hepatocellular carcinoma cells Huh-7." (PMID 31772204, 2019). "mTOR is frequently up-regulated in cancer including hepatocellular carcinoma (HCC) and its upregulation is associated with bad prognosis, poor tumor differentiation and earlier recurrence." (PMID 29167516, 2017).
hepatocellular carcinoma (continued). "A systematic review has shown mTOR inhibition to be associated with a significantly lower rate of hepatocellular carcinoma (HCC) recurrence versus standard calcineurin inhibitor therapy." (PMID 27807479, 2016). "Activation of the AKT/mTOR cascade and overexpression of c-Met have been implicated in the development of human hepatocellular carcinoma (HCC)." (PMID 26857837, 2016). "miR-199a-3p targets mTOR and c-Met in its role as a tumor suppressor in hepatocellular carcinoma and enhances susceptibility to hypoxia when its levels are restored." (PMID 24047116, 2013). "Our results show for the first time that salirasib inhibits the growth of human hepatoma cell lines through inhibition of proliferation and induction of apoptosis, which is associated with ras and mTOR inhibition." (PMID 20860815, 2010). "This study by Jianhua Li, Li Zhang, Hao Xing, and co‐workers reveals that the absence of intra‐tumoral tertiary lymphoid structure (TLS) is associated with enhanced mTOR signaling activation, indicating an unfavorable prognosis in hepatocellular carcinoma with liver transplantation (HCC‐LT)." (PMID 38498682, 2024). "A study has shown that SLFN11 can act as a tumor suppressor by suppressing the mTOR pathway by targeting RPS4X in hepatocellular carcinoma, which suggests that its mutation may lead to the loss of its inhibitory effect on mTOR." (PMID 37189093, 2023). "while nilocitin showed a G2/M and S cell cycle arrest as a consequence of the G1 phase, furthermore, the flavonoid hispidulin (4’,5,7-trihydroxy-6-methoxyflavone) causes ERS-mediated apoptosis in hepatocellular carcinoma cells by stimulating the AMPK/mTOR pathway." (PMID 37226153, 2023). "More specifically, PI3K/AKT/mTOR signalling levels induce the expansion of tumour-initiating cells by regulating cell cycle progression and are associated with recurrence and chemoresistance of hepatocellular carcinoma." (PMID 35165269, 2022). "Hepatocellular carcinoma (HCC) is frequently associated with mTOR signaling alterations." (PMID 35159342, 2022). "Similarly, as a probable transcription factor binding site of mTOR, variant rs1883965 was associated with esophageal carcinoma, gastric cancer, and hepatocellular carcinoma." (PMID 28977864, 2017). "However, several evidences indicated that phosphor-mTOR expression was closely linked to the poor prognosis of the patients with cervical adenocarcioma or hepatocellular carcinoma." (PMID 20003385, 2009). "HMGB1, stimulated by chemotherapeutic drugs, can be transported to the cytoplasm and promotes autophagy through activation of AMP-activated protein kinase (AMPK), which in turn causes inhibition of mTOR in hepatocellular carcinoma cells (HCC)." (PMID 38725632, 2024). "Additionally, LCH facilitates autophagy and apoptosis in hepatocellular carcinoma cells through the inactivation of the tongue cancer resistance-associated protein (TCRP1)/Protein kinase B (Akt)/mammalian target of rapamycin (mTOR) (TCRP1/Akt/mTOR) signaling pathway." (PMID 39339166, 2024). "For instance, patients with hepatocellular carcinoma (HCC) showed different survival associated with altered PI3K/AKT/mTOR signaling." (PMID 37237486, 2023). "Thus, we hypothesized that the local anesthetic ropivacaine may be implicated in hepatocellular carcinoma development by regulating the IGF-1 R-PI3K-Akt-mTOR signaling pathway." (PMID 34696683, 2021). "mTOR inhibitors serve as calcineurin inhibitor sparing agents in organ recipients with kidney dysfunction, hepatocellular carcinoma, or de novo neoplasms." (PMID 41400072, 2026). "More intriguingly, E2F1 plays a crucial role in activating the PI3K/AKT/mTOR signaling pathway in hepatocellular carcinoma cells." (PMID 39991770, 2025). "Studies reporting that apigenin induces apoptosis and autophagy by inhibiting the PI3K/Akt/mTOR pathway in hepatocellular carcinoma are aligned with our findings." (PMID 40432887, 2025).
hepatocellular carcinoma (continued). "SH3D21 stimulates the progression of hepatocellular carcinoma by activating the PI3K/AKT/mTOR signaling pathway, and SH3D21 can serve as a prognostic biomarker and therapeutic target for hepatocellular carcinoma." (PMID 40179068, 2025). "As a key regulator of cell growth and metabolism, mTOR promotes protein and lipid synthesis while inhibiting autophagy, providing the energetic and material basis for the proliferation and survival of hepatoma cells." (PMID 40430234, 2025). "The increased ChREBP activity involves the pro-oncogenic PI3K/AKT/mTOR signaling pathway that induces aberrant lipogenesis, thereby promoting hepatocellular carcinomas (HCC)." (PMID 40076869, 2025). "The Belgian group’s “one-two punch” strategy “CDC7 inhibitor-induced senescence” + “mTOR blocker-triggered apoptosis” effectively eliminated hepatocellular carcinoma cells with improved patient tolerance compared to conventional cytotoxic therapies." (PMID 40801613, 2025). "In hepatocellular carcinoma, aberrant activation of the PI3K/AKT/mTOR pathway—often due to PIK3CA mutations—is closely associated with aggressive tumor behavior and poor clinical outcomes." (PMID 41133538, 2025). "By inhibiting the PI3K/AKT/mTOR signaling pathway, they not only impede the progression of hepatocellular carcinoma but also concurrently modulate abnormal lipid metabolism and fibrosis development." (PMID 40807240, 2025). "Previous studies have shown that VER induces autophagy death by blocking the PI3K/Akt/mTOR signaling pathway, and inhibits the growth of hepatoma HepG2 cells in vitro and in vivo." (PMID 41382249, 2025). "Fisetin has been shown to suppress autophagy in hepatocellular carcinoma by activating PI3K/AKT/mTOR and inhibiting AMPK, resulting in autophagy inhibition and increased apoptosis." (PMID 40740483, 2025). "Overexpression of circZKSaa inhibits the development of hepatocellular carcinoma through the PI3K/Akt/mTOR pathway." (PMID 40387965, 2025). "This, in turn, elevated fatty acid and cholesterol biosynthetic activities, promoting hepatocellular carcinoma tumorigenesis and development through the activated mammalian target of rapamycin (mTOR) cascade." (PMID 40775221, 2025). "For example, FABP5 is highly expressed and promotes tumor proliferation in hepatocellular carcinoma, but its low expression suppresses tumor progression in colorectal cancer, a mechanism involving mTOR-mediated autophagy activation." (PMID 40717587, 2025). "Palbociclib has successfully induced cellular senescence in melanoma, liposarcoma, gastric cancer, and hepatocellular carcinoma by inhibiting the mammalian target of rapamycin (mTOR) signaling pathway." (PMID 40563615, 2025). "The clinical significance of the PI3K/Akt/mTOR pathway in hepatocellular carcinoma (HCC) is underscored by its high frequency of dysregulation and its profound impact on patient prognosis." (PMID 41208895, 2025). "Metformin plays a chemo-preventative role in the development of hepatocellular carcinoma by inhibiting mTOR." (PMID 40166471, 2025). "In hepatocellular carcinoma models, the inhibition of mTOR phosphorylation significantly activates autophagy and enhances radiation-induced apoptosis in tumor cells." (PMID 40725100, 2025). "In vivo studies further demonstrate that quercetin induces apoptosis in hepatocellular carcinoma cells through inhibition of the PI3K/Akt/mTOR signaling pathway." (PMID 41011149, 2025). "Studies have shown that HOXA5 acts as a tumor suppressor to inhibits tumor growth and recurrence by regulating the PI3K/AKT/mTOR signaling pathway in hepatocellular carcinoma." (PMID 38702814, 2024). "Previously, the silencing of one of the other Sm proteins (SmD1) was shown to suppress the PI3K/Akt/mTOR pathway in hepatocellular carcinoma cells." (PMID 39684842, 2024).